RNU4-51P (RNA, U4 small nuclear 51, pseudogene)
Gene: Small nuclear RNA gene on chromosome 2 (60,911,303 to 60,911,442, forward strand). Ensembl gene ENSG00000201076.
Homologues: Orthologues: chimpanzee U4 (98% identical), macaque U4 (94% identical). Paralogues in human: RNU4-49P (76% identical), RNU4-10P (76% identical), RNU4-46P (76% identical), RNU4-52P (76% identical), RNU4-66P (74% identical), RNU4-32P (71% identical), RNU4-81P (71% identical), RNU4-43P (71% identical), RNU4-17P (68% identical), RNU4-90P (68% identical), RNU4-50P (67% identical), RNU4-24P (66% identical), and 82 more.